KDM4C (lysine demethylase 4C)
Diseases named in the same sentence as KDM4C in open-access papers (continued):
Sharing a sentence is not in itself a finding about the gene and the disease.
neuroblastoma (3 papers, 2015 to 2022). Neuroblastoma (NB) is the most common solid, extracranial childhood tumor. "KDM3A has also been implicated in neuroblastoma metastasis and the HDM enzyme KDM4C has been shown to be a regulator of BCa lung metastasis and an activator of LOXL2 expression." (PMID 25488809, 2015). "Together, these findings suggest that MYCN, ATF4, and KDM4C work together to promote glutamine uptake and metabolism in MYCN-amplified neuroblastoma cells to meet the biosynthetic demands of cell growth and proliferation." (PMID 36077650, 2022). "MYCN, ATF4, and KDM4C all contribute to transcriptional upregulation of GOT1, GOT2, GPT, GPT2, and PSAT1 in neuroblastoma cells." (PMID 36077650, 2022). "The expression of CBS, CTH, SLC3A2, and SLC7A11 is transcriptionally upregulated by KDM4C and ATF4 in neuroblastoma cells, leading to a significant increase in the intracellular levels of cysteine." (PMID 36077650, 2022). "In neuroblastoma cells, ATF4 cooperates with the histone lysine demethylase KDM4C to transcriptionally upregulate the expression of enzymes for synthesis of eight non-essential amino acids, including alanine, arginine, asparagine, aspartate, cysteine, glutamate, glycine, and serine." (PMID 36077650, 2022). "Together, these findings suggest that the MYCN-ATF4 axis, in cooperation with epigenetic regulators, including KDM4C, is a major mechanism to increase the pools of amino acids for sustaining the MYCN-mediated growth program in neuroblastoma." (PMID 36077650, 2022).
Obesity (3 papers, 2018 to 2023). Accumulation of substantial excess body fat. "Also associated with obesity is KDM4C located at 9p24.1, a member of the JMJD2 family that promotes preadipocyte differentiation by repressing PPARγ transcriptional activation." (PMID 37955008, 2023). "Numerous enzymes associated with H3K9me3, the mark associated with heterochromatin, including acetyltransferases (SRC‐1/Ncoa1), deacetylases (Hdac3), methyltransferases (Suv39 h1 and G9a/Ehmt2), and demethylases (Jhmdh2a/Kdm3a, Jmjd2c/Kdm4c), have been linked to fatty liver, diabetes, and obesity." (PMID 29484800, 2018).
asthma (2 papers, 2023 to 2025). "Indeed, roles for other epigenetic effectors, including histone methylation and acetylation marks, have been implicated in the severity of asthma, and a genome-wide association study identified significant histone modifying enzyme (KDM2A, KDM4C, HDAC4, HDAC7 and HDAC9) polymorphisms in asthma." (PMID 40057553, 2025). "In addition, SETDB1 interacts with the asthma-related gene SETDB2; the latter antagonizes the KDM4C gene to control H3K9 methylation, which affects the expression of ORMDL3, a well-known asthma-related gene." (PMID 37569643, 2023).
bladder cancer (2 papers, 2017 to 2024). "The roles of KDM4 family members, including KDM4A, KDM4B, KDM4C and KDM4D, on bladder cancer remains unclear." (PMID 39461328, 2024).
cardiac hypertrophy (2 papers, 2016 to 2018). "Other lysine demethylases such as UTX/KDM6A, JMJD3/KDM6B, and JMJD2C/KDM4C have important roles in the differentiation of cardiac cells from their regulating progenitors, but their role in cardiac hypertrophy is elusive." (PMID 27722168, 2016).
invasive breast carcinoma (2 papers, 2012 to 2016). A carcinoma that infiltrates the breast parenchyma. "For instance, among erasers, we saw general cancer downregulation of KDM4C/JMJD2C (negatively associated with invasive breast cancer)." (PMID 27863398, 2016).
liver cancer (2 papers, 2021 to 2023). An epithelial or non-epithelial malignant neoplasm that arises from the liver. "Increased KDM4C transcripts were found in gastric and liver cancer patients based on TCGA database." (PMID 37848946, 2023).
myeloid malignancies (2 papers, 2022 to 2023). "In contrast, inactivation of Kdm4c alone did not reveal deleterious effects in normal HSCs, indicating a potential therapeutic window for defining it as a target in myeloid neoplasms." (PMID 35654819, 2022).
non-small cell lung carcinoma (2 papers, 2022 to 2023). A group of at least three distinct histological types of lung cancer, including non-small cell squamous cell carcinoma, adenocarcinoma, and large cell carcinoma. "We found a significant association between tuberculosis and KDM4C, a lysine demethylase that was also shown to be significantly associated with non-small cell lung carcinoma." (PMID 37108169, 2023).
Prostate Tumors (2 papers, 2012 to 2019). "Compared to the normal prostate tissues, the KDM4C mRNA expression level was higher in prostate tumors." (PMID 31766290, 2019). "Finally, we determined the protein level of KDM4C in prostate tumors using immunohistochemical (IHC) staining." (PMID 31766290, 2019).
renal cell carcinoma (2 papers, 2019). "Alteration of KDM4C gene has been shown to occur in renal cell carcinoma." (PMID 31575031, 2019).
acute kidney injury (1 paper, 2022). Sudden and sustained deterioration of the kidney function characterized by decreased glomerular filtration rate, increased serum creatinine or oliguria. "The purpose of this study was to examine the roles of KDM4C in kidney development and acute kidney injury (AKI)." (PMID 36012577, 2022).
acute leukemia (1 paper, 2016). A clonal (malignant) hematopoietic disorder with an acute onset, affecting the bone marrow and the peripheral blood. "Pharmacological inhibition of KDM4C/PRMT1 suppresses transcription and transformation ability of MLL fusions and MOZ-TIF2, revealing a tractable aberrant epigenetic circuitry mediated by KDM4C and PRMT1 in acute leukemia." (PMID 26766589, 2016).
Alzheimer disease (1 paper, 2023). A progressive, neurodegenerative disease characterized by loss of function and death of nerve cells in several areas of the brain leading to loss of cognitive function such as memory and language. "Regarding lysine demethylases, inhibitors of KDM1A are in clinical trials for refractory cancers and Alzheimer’s disease, while inhibitors of KDM4 and KDM4C are only being studied for refractory cancers, and drug discovery in this field may be realized in the near future." (PMID 36975603, 2023).
cervical carcinoma (1 paper, 2025). A carcinoma arising from either the exocervical squamous epithelium or the endocervical glandular epithelium. "Histone KDM6B (lysine demethylase) and KDM4C are found to be higher in cervical carcinoma." (PMID 40159638, 2025).
chronic myeloid leukemia (1 paper, 2018). "To this end, we used the human chronic myeloid leukemia cell line K562, which displays higher levels of endogenous KDM4C in comparison to the non-malignant HEK293 cell line." (PMID 29682190, 2018).
metastatic prostate carcinoma (1 paper, 2025). A carcinoma that arises from the prostate gland and has spread to other anatomic sites. "Also the expression of KDM4C was higher in metastatic prostate cancer patients, and KDM4C knockdown or pharmacological inhibition using SD70 significantly reduced cell migration and invasion, which was associated with the increased level of E-cadherin." (PMID 40940894, 2025).
oral cancer (1 paper, 2025). "To further investigate the clinical relevance of KDM4C and GATA1, we conducted an immunohistochemical (IHC) analysis on 85 paraffin-embedded oral cancer specimens from Taipei Veterans General Hospital patients." (PMID 40259045, 2025).
paraganglioma (1 paper, 2022). A benign or malignant neoplasm arising from paraganglia located along the sympathetic or parasympathetic nerves. "KDM4C expression is related to a bad prognosis for Rectum Adenocarcinoma and Pheochromocytoma and Paraganglioma." (PMID 35480330, 2022).
rheumatoid arthritis (1 paper, 2026). A chronic, systemic autoimmune disorder characterized by inflammation in the synovial membranes and articular surfaces. "This study aims to investigate structural and expression-level alterations in the histone demethylase KDM4C gene in patients with rheumatoid arthritis (RA) and elucidate its role in the disease's epigenetic basis." (PMID 41680357, 2026).
cancer (65 papers, 2012 to 2026). A tumor composed of atypical neoplastic, often pleomorphic cells that invade other tissues. "Overexpression of KDM4C and related demethylases has been linked to increased tumor growth, invasion, and metastasis in various cancers." (PMID 41505486, 2026). "Spearman’s coefficient analysis revealed a significant correlation between KDM4C expression and clinical parameters (pN, pM, and pStage), suggesting a strong association between KDM4C and cancer progression." (PMID 40259045, 2025). "KDM4C is amplified or overexpressed in many human cancers and is closely associated with the degree of malignancy of the tumors." (PMID 38623585, 2024). "KDM4C is a nuclear protein that converts trimethylated histone residues to the dimethylated form and has been implicated in regulating cancer proliferation." (PMID 35903898, 2022). "Finally, development of specific pharmacologic KDM4C inhibitors will allow pre-clinical validation of demethylases as relevant clinical targets in JAK2-mutated cancers." (PMID 35654819, 2022). "Most recently, KDM4C has been described as a regulator of stemness, cancer cell resistance and cancer progression in various cancer models and KDM4C germline variants may increase multi-cancer vulnerability through dysregulation of target histone methylation." (PMID 35654819, 2022). "By integrating high-resolution JmjC domain analysis with insilico screening, we aim to develop selective KDM4C inhibitors, advancing precision oncology and novel cancer therapies." (PMID 41505486, 2026). "Structural insights into the JmjC catalytic domain further facilitate rational drug design, establishing KDM4C as a promising candidate for the development of selective inhibitors aimed at disrupting oncogenic transcriptional programs in cancer therapy." (PMID 41505486, 2026). "Targeting KDM4C is particularly relevant in cancer, as histone methylation dynamically regulates gene expression involved in cell proliferation and survival." (PMID 41505486, 2026). "Since this computational study highlights promising natural polyphenolic compounds as potential KDM4C inhibitors for cancer therapy, several limitations must be addressed before clinical translation." (PMID 41505486, 2026). "KDM6B is responsible for colony formation ability while KDM4C increases cancer aggressiveness, respectively." (PMID 40159638, 2025). "Our results support the therapeutic potential of KDM4C inhibition and provide a rationale for targeting heme metabolism in aggressive cancers." (PMID 40259045, 2025). "We further demonstrate that Inhibiting KDM4C reduces cancer progression, as validated in zebrafish xenotransplantation and mouse graft models." (PMID 40259045, 2025). "Given the oncogenic role of KDM4C in various cancers, we evaluated its therapeutic potential using small-molecule inhibitors." (PMID 40259045, 2025). "These family members are involved in diverse biological pathways linked to cancer such as Akt-mTOR signaling for KDM4A, Wnt signaling for KDM4B, targeting pluripotency factors for KDM4C, and hypoxia-inducible factor 1 signaling for KDM4D." (PMID 36975603, 2023). "KDM4C, which is a histone lysine demethylase, has been proposed to participate in the malignant transformation and progression of several types of cancer." (PMID 37117173, 2023). "By using TCGA pan-cancer analysis, we found that the expression of KDM4C was significantly higher in CRC than in normal tissues." (PMID 35871166, 2022). "As an H3K9me3 and H3K36me3/2 demethylase, lysine demethylase 4c (Kdm4c) has been reported to be an oncogene in cancers that regulates cell proliferation by activating the genes involved in cell signaling, cell cycle and translation." (PMID 35886932, 2022). "Functionally, KDM4C knockout decreased cancer progression in a zebfrafish xenotransplantation model." (PMID 35903898, 2022).
cancer (continued). "Accumulating evidence supports the oncogenic potential of KDM4A, KDM4B, and KDM4C, which are overexpressed in several types of cancer, including PCa." (PMID 35534851, 2022). "KDM4C (also known as GASC1) is amplified in many cancers including BC, mainly in basal-like and in ER- and PR- subtypes, making this enzyme a negative prognostic marker." (PMID 34778065, 2021). "Accumulating evidence suggests that KDM4C is a candidate oncoprotein that is amplified or overexpressed in various cancer types." (PMID 33558705, 2021). "KDM4C regulates expression of genes involved in stem cell self-renewal and induces phenotypic changes in cancer cells." (PMID 34778065, 2021). "Aberrant expression of KDM4C has been observed in several types of cancers, indicating its oncogenic roles in tumorigenesis." (PMID 33558705, 2021). "In normal and some cancer cells, KDM4C regulates cell proliferation by activating the target genes that are involved in cell signaling, cell cycle, and translation." (PMID 33462212, 2021). "Although the role of KDM4C in PCa is not well understood, KDM4C has been reported to be an oncogene in other cancers." (PMID 31766290, 2019). "Our current studies provide the key in vivo experimental evidence demonstrating the requirement of KDM4C for cancer development and its functional crosstalk with PRMT1 in the establishment of histone codes for transcriptional deregulation in AML." (PMID 26766589, 2016). "In accord with this, recent analysis of the Cancer Genome Atlas revealed that KDM4C is lost in some cancer types and overexpressed in others." (PMID 24728997, 2014). "We concluded that similar to KDM4C knockdown, upregulation of KDM4C promotes mitotic chromosome missegregation that can potentially lead to CIN found in cancer driven by KDM4C overexpression." (PMID 24728997, 2014). "Thus, inhibiting KDM4C offers a promising strategy for restoring epigenetic control and suppressing cancer progression." (PMID 41505486, 2026). "Similarly, SD70 exhibited an IC50 range of 1–30 μM in various Cancer Cell lines, effectively inhibiting KDM4C and other KDMs." (PMID 41505486, 2026). "Interestingly, KDM4C has been reported to be overexpressed in multiple cancer types, including breast and prostate cancers, where it plays a key role in promoting cell proliferation, gene regulation, and tumor progression." (PMID 40259045, 2025). "However, further research is needed to fully understand the role of KDM4C in cancers and to develop effective KDM4C-targeted therapies." (PMID 38623585, 2024). "Given that these KDM4 demethylases, especially KDM4B and KDM4C, are involved in an array of cancers, targeting the catalytic activity of these demethylases could have therapeutic potential." (PMID 36975603, 2023). "Interestingly, SSK1 alone was insufficient to induce cell death, but eliminated the cancer cells pre-treated with KDM4C selective inhibitor (QC6352)." (PMID 37848946, 2023). "KDM4C contributes to tumor progression across human cancers, suggesting that it may serve as a promising therapeutic target for cancers." (PMID 37848946, 2023). "In addition, growing evidence has reported that KDM4C is overexpressed and promotes tumorigenesis in multiple types of human cancer." (PMID 37117173, 2023). "KDM4C (JMJD2C) is a jumonji domain-containing protein and acts as a trimethylation-specific demethylase that contributes to epigenetic regulation of both oncogene and tumor suppressor genes and is frequently overexpressed in human cancers." (PMID 35654819, 2022). "We next sought to evaluate whether KDM4B is the key member of the KDM4 family (KDM4A, KDM4B, and KDM4C) for controlling c-Myc to regulate cancer metabolism." (PMID 34335964, 2021). "Furthermore, the important role of KDM4C in CSC maintenance has made this epigenetic factor a promising target for cancer intervention." (PMID 32908544, 2020).
cancer (continued). "Finally, miR-486-5p also promote the expression of five genes with promoting cancer roles: KDM4C, PPARD, KLF4, STAT3, and TCF7l2." (PMID 33227890, 2020). "In addition, KDM4C can interact with chromosomes during mitosis to regulate the breast cell proliferation, migration, and invasion, suggesting a common oncogenic role of KDM4C in different cancer types." (PMID 32908544, 2020). "The factors KDM4C and BHLHE40 were found to be overexpressed only in the tumors with c-met mutation, validating the use of iPSC technology for the analysis of these hereditary cancers." (PMID 31575031, 2019). "In this respect, silencing KDM4C expression by siRNA led to abnormal mitotic cells, as well as inhibition of cancer cell growth and cell death in KYSE150 and U2OS cells, rendering these enzymes an attractive druggable target both for research as well as for anti-cancer therapeutics." (PMID 29682190, 2018). "It should be noted however that we cannot exclude the existence of additional yet unknown mechanisms that contribute to CIN found in cancer driven by either lack or overactivity of KDM4C lysine demethylase." (PMID 24728997, 2014). "Among the most important histone demethylases associated with the development of cancer are LSD-1/KDM1A, and members of the Jumonji family JARID1A-1C/KDM5A-5C, JHDM1B/KDM2B, JMJD2C/KDM4C, JMJD2A/KDM4A, JMJD3/KDM6B, and UTX/KDM6A, which will be analyzed in detail in the following paragraphs." (PMID 24280700, 2012). "Furthermore, enhanced KDM4 activity or increased levels of KDM4B and/or KDM4C caused by intermittent hypoxia may also impact tumors, as the KDM4 group is associated with various cancers." (PMID 36174675, 2022). "To further substantiate our findings and expand the context of KDM4C/GATA1's regulatory role in HNSCC, we analyzed the relationship between heme metabolism and other cancer-related pathways using the TCGA HNSCC dataset." (PMID 40259045, 2025). "Amplified demethylases with the highest prevalence, above 10% in basal cancers, included H3K4 demethylases KDM5A from locus 12p13.33 and KDM5B from 1q32.1 and H3K9 demethylase KDM4C from 9p24.1." (PMID 37504297, 2023). "This highlighted the crucial role of ALKBH5 in maintaining cancer stem cell (CSC) renewal and cancer occurrence and development through the KDM4C-ALKBH5-AXL Signaling Axis." (PMID 36035182, 2022). "Accumulating evidence suggests the cancer drivers KDM4A, KDM4B, and KDM4C are overexpressed leading to the efficient growth, in a variety of human malignancies including breast, colorectal, lung, prostate, and other cancers." (PMID 36520265, 2022). "Suppression of H3K9me2/me3 demethylase activity such as KDM3A (JMJD1A), KDM4C (JMJD2C), and KDM7C (PHF2) in tissue specific stem cell cultures and cancer cells can lead to premature senescence, increased DNA damage and genomic instability." (PMID 34017357, 2021). "Similarly, seven genes (SGCZ, KANK1, KDM4C, KCNMA1, ZNF263, CDH4, NCAM2) contain partial CNV duplications in both BD‐cancer and BD‐only patients, but the deleted loci are different." (PMID 39140252, 2025). "Indeed, we noted a robust correlation in the expression of KDM4A, KDM4B, KDM4C and KDM4D across all tumour samples in the TCGA pan‐cancer database." (PMID 38390756, 2024). "The KDM4C gene is a HIF-1 target gene; therefore the interaction of JMJD2C with HIF-1α may provide a positive feedback mechanism in cancer cells by amplifying HIF-1–mediated transactivation." (PMID 36899934, 2023). "This analysis, applied to primary cancers with and without c-met mutation, showed overexpression of the BHLHE40 and KDM4C only in the c-met-mutated PRCC tumors, as predicted by c-met-mutated embryoid bodies transcriptome." (PMID 31575031, 2019). "However, the regulatory mechanisms and roles of KDM4C in cancer radioresistance have not yet been investigated." (PMID 33558705, 2021).